SOST (sclerostin)
Diseases named in the same sentence as SOST in open-access papers (continued):
Sharing a sentence is not in itself a finding about the gene and the disease.
Hypertension (24 papers, 2018 to 2025). The presence of chronic increased pressure in the systemic arterial system. "The current study aimed to explore the association of serum sclerostin or DKK1 with PAD in patients with hypertension." (PMID 40731833, 2025). "We also highlight a potential (but borderline significant in our study) causal relationship between genetically predicted lower levels of sclerostin and increased risk of myocardial infarction and hypertension." (PMID 39537602, 2024). "Genetically predicted lower sclerostin levels were found to associate with higher risk of hypertension, MI, type 2 DM, and increased CAC." (PMID 37096546, 2023). "MR using both cis and trans instruments suggested that lower sclerostin increased hypertension risk (OR 1.09 [95% CI 1.04–1.15]), but otherwise had attenuated effects." (PMID 37096546, 2023). "In multivariate linear regression analyses, the presence of hypertension, NaCl intake, and serum sclerostin remained strongly associated with urinary calcium (st. β 0.30, p < 0.01; st. β 0.31, p = 0.02; st. β 0.26, p = 0.01, respectively)." (PMID 37568429, 2023). "{FIG1} Whereas unadjusted analyses showed a positive association between sclerostin and hypertension, this was largely attenuated after adjustment for confounders, and CIs overlapped the null in the meta‐analysis." (PMID 34738659, 2022). "Multivariable forward stepwise linear regression analysis also showed that serum sclerostin level (β = 0.255, adjusted R2 change: 0.146, p = 0.003) was positively associated with cfPWV values in patients with hypertension." (PMID 30482161, 2018). "On the other hand, our finding that sclerostin lowering only increased the risk of hypertension when using the cis+trans instrument could result from pleiotropy." (PMID 37096546, 2023). "This study provides genetic evidence to suggest that lower levels of sclerostin may increase the risk of hypertension, type 2 DM, MI, and the extent of CAC." (PMID 37096546, 2023). "These latter analyses identified an effect of sclerostin inhibition on risk of hypertension." (PMID 37490188, 2023). "From a clinical standpoint, these data indicate the clinical value of serum sclerostin as a screening biomarker of hypertension in patients at higher risk of developing PAD and those who may benefit from a timely diagnosis or a more aggressive preventive intervention." (PMID 40731833, 2025). "Therefore, among alcoholics, sclerostin constitutes a risk factor for the development of vascular calcification, that, in our study, seems to be more important than the classic risk factors hypertension, kidney failure, cholesterol, or triglycerides." (PMID 36895513, 2023). "An independent association was observed between increased serum sclerostin levels and PAD in patients with hypertension." (PMID 40731833, 2025). "BMD corrected for BMI at lumbar spine was inversely associated with UCa in a univariate analysis, but only serum sclerostin, hypertension, and NaCl intake were independent determinants of UCa in the multivariate model." (PMID 37568429, 2023). "In conclusion, in addition to hypertension and elevated salt intake, circulating sclerostin was shown to be a strong and independent determinant of urinary calcium among stone-forming patients." (PMID 37568429, 2023). "Associations with cardiac mortality and coronary artery severity were partially attenuated after adjustment for risk factors potentially related to sclerostin, namely LDL and HDL cholesterol, log triglycerides, DM, hypertension, eGFR, and apolipoprotein A‐I." (PMID 34738659, 2022). "Multivariate analysis exploring the relationship between hypertension, sclerostin and creatinine by logistic regression showed that the only variable selected was creatinine (p = 0.012)." (PMID 35807755, 2022).
Hypertension (continued). "In a multiple linear regression model, serum OPG proved to be a strong predictor of PWV when the model was adjusted for hypertension, left-ventricular end-diastolic diameter, serum sclerostin, and exercise level." (PMID 33923139, 2021). "Higher sclerostin levels were observed in patients with a history of smoking (59.08 vs 45.93 pmol/l; median, p = 0.063) and hypertension (47.75 vs 34.41 pmol/l; median, p = 0.056) compared to non-smokers and patients with no history of hypertension." (PMID 32458213, 2020). "Age, BMI, DM, hypertension, pulse pressure, eGFR, and sclerostin (p < 0.05) were independent variables and the presence of carotid atherosclerotic plaques was the dependent variable." (PMID 32458213, 2020). "Therefore, serum sclerostin has a clinically important predictive value for PAD in this population with hypertension." (PMID 40731833, 2025). "Also, the results highlighted a potential causal relationship between genetically predicted lower levels of sclerostin and myocardial infarction (OR = 1.35 [0.98, 1.87]) and hypertension (OR = 1.03 [0.99, 1.07])." (PMID 40429697, 2025). "If validated, the results may support the use of circulating sclerostin and DKK1, which can be easily accessed and are noninvasive, as biomarkers for risk stratification in the context of PAD among patients with hypertension." (PMID 40731833, 2025). "Notably, serum sclerostin levels, hypertension, and salt intake were shown to be independent determinants of urinary calcium." (PMID 37568429, 2023). "Lower sclerostin levels showed a causal effect on hypertension risk using the combined cis and trans instruments, without evidence of reverse causality." (PMID 37096546, 2023). "This may suggest that, at least in alcoholics, sclerostin may be a factor related to vascular damage, independent on hypertension and/or kidney failure (a suggestion also derived from the reported results of the logistic regression analysis)." (PMID 36895513, 2023). "Therefore, when hypertension is present, the relationship of sclerostin with brain atrophy is less marked." (PMID 36895513, 2023). "Moreover, the short duration of arterial hypertension in our patients excluded advanced arterial lesions and masked a possible relationship with sclerostin observed in adult studies." (PMID 34441870, 2021). "This potentiating effect is a speculative possibility supported by the observation that the control group of non-drinkers show a very low proportion of vascular calcifications despite a similar prevalence of hypertension and similar sclerostin levels than the patients." (PMID 36895513, 2023). "The implication of this study is that sclerostin is both a marker and mediator of PAD measured using ABI in individuals with hypertension." (PMID 40731833, 2025). "sclerostin, and Dkk-1 as independent predictors for LVM, which shows that hypertension is a positive predictor for LVM (with P value <0.01 and confidence interval (CI) = 10.70 to 70.50) and shows also that HDL and s." (PMID 34603797, 2021). "In contrast, we observed little evidence of a causal effect of lower sclerostin on AAC, CAD, risk of stroke (and its subtypes), risk of hypertension, and lipid subtypes." (PMID 37096546, 2023). "Patients with hypertension showed a trend to higher sclerostin levels than patients without hypertension." (PMID 35807755, 2022). "Predictive models included age (for both outcomes), hypertension, Framingham risk score and C-reactive protein (for PWV), but not sclerostin." (PMID 36517533, 2022). "sclerostin, and Dkk-1 as independent predictors for LVMI, which shows that hypertension is a positive predictor for LVMI (with P value =0.050 and CI = −0.025 to 36.80), while serum Dkk-1 was an independent negative predictor for LVMI (with P value < 0.05 and CI = −0.478 to −0.010)." (PMID 34603797, 2021).
Hypertension (continued). "In our study, serum sclerostin was a significant predictor of AS in the subgroup of PWV < 10 m/s in a multiple linear regression model containing IMT, left-ventricular end-diastolic diameter, and hypertension." (PMID 33923139, 2021). "The plaque group had higher serum levels of sclerostin (p = 0.013), were older (p < 0.001), and had a higher pulse pressure (p = 0.036), and higher prevalence of hypertension (p = 0.007) and DM (p < 0.001) compared to the non-plaque group." (PMID 32458213, 2020). "Participants with hypertension had increased sclerostin levels compared to those without this condition (52.25 ± 24.26 vs 41.97 ± 16.98 pmol/L, p = 0.012)." (PMID 29928063, 2018). "For the inhibitors of the Wnt/β-catenin pathway, serum sclerostin levels, not DKK1, are positively correlated with cfPWV values in patients with hypertension." (PMID 30482161, 2018). "With linear regression analysis for LVMI, there was a nonsignificant prediction of age, HDL, MVC, and serum sclerostin for LVMI; on the other hand, serum DDK-1 was a significant negative indicator for LVMI and hypertension was a weak significant positive predictor for LVMI (P value = 0.05)." (PMID 34603797, 2021).
Hyperglycemia (23 papers, 2017 to 2025). An increased concentration of glucose in the blood. "It has been shown that sclerostin is stimulated in endothelial cells by pro-atherosclerotic factors including hyperglycemia, which increases the susceptibility of LDL-c to oxidation." (PMID 37919715, 2023). "Beyond the mechanics, T1DM and T2DM impair osteocyte function, causing an increase in expression of sclerostin, an endogenous inhibitor of bone formation, and may be directly related to hyperglycaemia reducing bone cell activity and, subsequently, levels of circulating bone turnover markers." (PMID 36190648, 2022). "Elevated SOST expression under HG is consistent with previous studies demonstrating suppression of the Wnt/β-catenin pathway in osteocytes in response to hyperglycemia." (PMID 40401158, 2025). "However, serum levels of SOST are significantly increased in patients with T2DM and femur fractures, suggesting that hyperglycemia may increase the expression of SOST by antagonizing canonical Wnt signaling to cause bone resorption beyond bone formation and increase adipocytogenesis." (PMID 37106471, 2023). "Sclerostin is also related with metabolic disturbances such as hyperglycemia in the studied population." (PMID 36675692, 2022). "Hyperglycaemia in diabetic patients directly increases the production of sclerostin and therefore inhibits bone formation by downregulating the Wnt pathway." (PMID 34690653, 2021). "Hyperglycaemia in diabetic patients increases proinflammatory cytokines (interleukin-1 and interleukin-6), which induce osteocytes to produce sclerostin." (PMID 34690653, 2021). "Hyperglycaemia also indirectly increases sclerostin levels by accumulating AGEs inside the bone collagen." (PMID 34690653, 2021). "For example, hyperglycemia and advanced glycation end-products (AGEs) that emerge in the chronic hyperglycemia state of DM can increase the production of sclerostin in osteocytes." (PMID 33308247, 2020). "Mechanisms to explain this observation come from in vitro studies, which report that hyperglycemia increases sclerostin expression by osteocyte cell lines." (PMID 29946974, 2018). "Antioxidant treatment and TNF-α knockdown attenuate high glucose-induced sclerostin expression, suggesting that hyperglycemia induces high sclerostin expression via enhancing the production of reactive oxygen species and TNF-α." (PMID 29240821, 2017). "Similarly, exogenous SCL induced the expression of these matrix-degrading enzymes, highlighting the dual impact of hyperglycemia and sclerostin on osteocyte-driven matrix remodeling." (PMID 40352664, 2025). "The upregulation of SOST under HG conditions suggests that targeting sclerostin, a known inhibitor of bone formation, may help counteract the suppressive effects of hyperglycemia on bone formation." (PMID 40401158, 2025). "Additionally, the positive correlation between placental sclerostin levels, pregestational maternal body mass index, and fasting glucose concentrations suggests an adaptive mechanism in response to maternal hyperglycemia." (PMID 40943516, 2025). "The up-regulation of sclerostin in T2D patients could be produced by the hyperglycemia that has both a direct effect on bone cells and indirect effects through the formation of advanced glycation end-products affecting bone." (PMID 37919715, 2023). "The observed overexpression in the placental sclerostin/LRP5 pathway in the studied GDM placentas might represent the development of an adaptive mechanism in face of maternal hyperglycemia." (PMID 36947076, 2023). "Sclerostin is also related to metabolic disturbances such as hyperglycemia in this population." (PMID 36675692, 2022). "In addition, hyperglycemia induces higher serum levels of sclerostin, a bone-signaling peptide secreted from the osteocyte, and inhibits osteoblast activity by blocking the noncanonical Wnt signaling pathways." (PMID 33776769, 2021).
Hyperglycemia (continued). "Moreover, hyperglycaemia indirectly accumulates AGEs in the bone collagen, leading to increased sclerostin." (PMID 34690653, 2021). "In addition, as sclerostin probably induces hyperglycemia and hyperlipedemia via its actions in adipose tissue, the roles of sclerostin during CVD development may be multifaceted but remain largely unknown." (PMID 32544571, 2020). "Furthermore, hyperglycemia may have a direct influence on bone cells by increasing the expression of sclerostin in osteocytes to inhibit bone formation." (PMID 30866902, 2019). "Hyperglycemia also modulates some important bone turnover biomarkers such as bone morphogenetic protein-2 (BMP-2), which promotes osteoblast differentiation, and sclerostin, which retard bone formation." (PMID 35928902, 2022). "Previous in-vitro studies indicate that hyperglycemia reduces BMP-2 levels in bone mesenchymal stem cells and increases sclerostin levels in murine cell lines." (PMID 35928902, 2022). "We may conclude that sclerostin is a possible marker of metabolic disturbances such as hyperglycemia in non-dialysis CKD male patients." (PMID 36675692, 2022).
osteosarcoma (21 papers, 2018 to 2025). A usually aggressive malignant bone-forming mesenchymal neoplasm, predominantly affecting adolescents and young adults. "SOST deficiency triggers proliferative and invasive capacities and decreases apoptotic levels of human retinoblastoma cells and osteosarcoma cells via activation of Wnt/β-catenin signaling." (PMID 35785219, 2022). "Indeed, SOST gene (encoding Sclerostin) silencing, leading to Wnt/β-catenin activation, down-regulates capsase-3 dependent apoptosis in osteosarcoma cells." (PMID 34062831, 2021). "However, it is reported that elevated Wnt/b-catenin signaling pathway, activated by inhibition of sclerostin by Scl-ab, is associated with osteosarcoma." (PMID 32664215, 2020). "However, osteogenic drugs such as parathyroid hormone injections, which activate Wnt signaling by downregulating sclerostin, are suspected of increasing the risk of osteosarcoma due to the excessive bone formation caused by their long duration of treatment in animal experiments." (PMID 34885123, 2021). "Sclerostin has also been shown to suppress the proliferative and migratory capacity of osteosarcoma cells, and administration of sclerostin inhibits tumor growth in mice and prolongs animal survival." (PMID 38247829, 2024). "Recent data report anti-tumoral effects of sclerostin administration in animal models of osteosarcoma, where it inhibits the growth and migration of osteosarcoma cells." (PMID 37755271, 2023). "For prostate cancer, sclerostin has anti-tumor effects in osteosarcoma, as administration of recombinant sclerostin inhibited tumor growth and migration and improved survival in a mouse model of osteosarcoma." (PMID 37174109, 2023). "Sclerostin silencing resulted in increased activation of the Wnt/β-catenin, leading to increased proliferation of osteosarcoma cells." (PMID 37755271, 2023). "Several studies have reported that SOST-mediated Wnt/β-catenin pathway participates in retinoblastoma progression and osteosarcoma." (PMID 35785219, 2022). "There are several advantages in the clinical application of sclerostin for the treatment of osteosarcoma." (PMID 34885123, 2021). "The administration of sclerostin to osteosarcoma cells significantly inhibited the growth and migratory ability of osteosarcoma cells." (PMID 34885123, 2021). "In a mouse model that was subcutaneously transplanted with a mouse osteosarcoma cell line, sclerostin was found to inhibit tumor growth and prolong overall survival." (PMID 34885123, 2021). "Sclerostin was administered to mice that were subcutaneously transplanted with the murine osteosarcoma cell line LM8." (PMID 34885123, 2021). "Here, we investigated the antitumor effect of sclerostin against osteosarcoma and found that sclerostin suppressed the proliferative capacity and migratory ability of osteosarcoma cells." (PMID 34885123, 2021). "In human osteosarcoma Saos2 cell line, Runx2 was found to increase SOST gene expression by binding to the proximal promoter." (PMID 34830568, 2021). "In this study, we showed that sclerostin, a canonical Wnt pathway inhibitor, suppresses the proliferation and migration ability of mouse and human osteosarcoma cell lines." (PMID 34885123, 2021). "In order to confirm the effect of sclerostin on the Wnt pathway of osteosarcoma, we examined the expression level of β-catenin in LM8 and 143B by Western blot assay." (PMID 34885123, 2021). "In order to evaluate the effect of sclerostin on the proliferative potential of the mouse osteosarcoma cell line, an alamarBlue assay was performed." (PMID 34885123, 2021). "Bone formation is a shared phenomenon in all types of osteosarcomas, and sclerostin is an extracellular soluble factor secreted by osteocytes that prevents bone formation by inhibiting the Wnt signaling pathway." (PMID 34885123, 2021). "Osteosarcoma model mice inhibited tumor growth and prolonged survival periods by the administration of sclerostin." (PMID 34885123, 2021).